CD300LG (CD300 molecule like family member g)
Description:
Receptor which may mediate L-selectin-dependent lymphocyte rollings. Binds SELL in a calcium dependent manner. Binds lymphocyte (By similarity).
Synonyms: CLM-9; TREM-4; CLM9; TREM4; NEPMUCIN
Tractability: Antibody: its Gene Ontology location is reachable by antibodies, with high confidence; UniProt places it where antibodies can reach, with medium confidence; UniProt predicts a signal peptide or a membrane-spanning region.
Gene: Protein-coding gene on chromosome 17 (43,847,114 to 43,863,639, forward strand). Ensembl gene ENSG00000161649.
Subcellular location: Apical cell membrane; Basolateral cell membrane; Endosome, multivesicular body membrane
Subcellular location (Human Protein Atlas): Calyx
Pathways (Reactome):
Immune System: Immunoregulatory interactions between a Lymphoid and a non-Lymphoid cell
Gene Ontology:
Molecular function: protein binding; transmembrane signaling receptor activity
Biological process: signal transduction
Cellular component: apical plasma membrane; basolateral plasma membrane; plasma membrane; multivesicular body membrane
Genetic constraint (gnomAD): Loss-of-function variants: 28 observed, 31.13 expected, observed/expected ratio (o/e) 0.9, 90% interval 0.67 to 1.23. The upper end of that interval is the gene's LOEUF score, 1.23, which puts it in group 5 of 6, group 1 being the genes least tolerant of losing a copy. Missense variants: 393 observed, 422.07 expected, observed/expected ratio (o/e) 0.93, 90% interval 0.86 to 1.01. Synonymous variants: 172 observed, 178.24 expected, observed/expected ratio (o/e) 0.97, 90% interval 0.85 to 1.1.
Homologues: Orthologues: chimpanzee CD300LG (98% identical), macaque CD300LG (81% identical), dog CD300LG (69% identical), mouse Cd300lg (61% identical), rabbit CD300LG (61% identical), rat Cd300lg (61% identical). Paralogues in human: PIGR (21% identical), CD300A (20% identical), FCAMR (19% identical), CD300C (18% identical), FCMR (18% identical), CD300LF (16% identical), CD300E (15% identical), CD300LB (15% identical), TMIGD3 (15% identical), TREML1 (15% identical), CD300H (15% identical), CD300LD (15% identical), and 1 more.
Diseases named in the same sentence as CD300LG in open-access papers:
CD300LG is named in the same sentence as 14 diseases in open-access papers, as found by Europe PMC text mining. Sharing a sentence is not in itself a finding about the gene and the disease. The quoted sentences say what the papers report.
breast carcinoma (4 papers, 2019 to 2025). "The immune function-related genes CD300LG and PIGR were also detected as downregulated in breast cancer." (PMID 31182966, 2019). "There is a number of scientific research for each of the top 10 mRNA genes, well-documenting their significance and association with cancerogenesis: ADAMTS5, TMEM220, ARHGAP20, MICU3; or precisely with breast cancer: COL10A1, MMP11, CAVIN2 (formerly known as SDPR), PLPP3, MME, and CD300LG." (PMID 40724805, 2025). "Though CIDEC and CD300LG have been shown to be downregulated in other breast cancers, they have not previously been identified in TNBC." (PMID 39409999, 2024). "Finally, 6 upregulated DEGs (CST2, DRP2, CLEC5A, SCD, KIAA1211, DTL) and 6 downregulated DEGs (STAC2, BTNL9, CA4, CD300LG, GPIHBP1 and PIGR), were confirmed in a quantitative real time PCR comparison of breast cancer and paracancerous breast tissues from 8 clinical specimens." (PMID 31182966, 2019).
diabetes (2 papers, 2013 to 2025). "In contrast, nepmucin/CD300LG was induced in the high endothelial venule-like blood vessels of chronically inflamed pancreatic islets in an animal model of non-obese diabetes." (PMID 24376728, 2013).
lung carcinoma (2 papers, 2024 to 2025). "Noteworthy, CD300A overexpression has been found to inhibit progression of NSCLC and decreased expression of CD300LG (> 90% expression decrease) has been reported in lung cancers." (PMID 38704802, 2024).
Obesity (2 papers, 2016 to 2019). Accumulation of substantial excess body fat. "Inflammation and immunity: Culture with Dex led to a more robust increase in Abdsc than Om of CD300LG which is implicated in T-cell recruitment and P2RY14/GPR105 (Cluster 1) which modulates macrophage recruitment in diet-induced obesity." (PMID 28005982, 2016). "Genes functionally non-reported in adipose tissue showed a link with a GWAS obesity trait (SLC19A3 and UPK3B genes) and a GWAS blood lipids trait (LVRN, CD300LG, and HAS1 genes)." (PMID 30816281, 2019).
breast tumor (1 paper, 2024). "CD300 Molecule Like Family Member G (CD300LG), the second-ranked downregulated TNBC mechanistic marker in our analysis, was previously reported as being downregulated in breast tumor tissue." (PMID 39409999, 2024).
cervical cancer (1 paper, 2020). A primary or metastatic malignant neoplasm involving the cervix. "While BIRC3 and CD300LG may play a role in the pathophysiology of cervical cancer metastasis, our gene expression study simply suggests a correlative connection." (PMID 32595829, 2020).
Hypertension (1 paper, 2022). The presence of chronic increased pressure in the systemic arterial system. "One study explored CD300LG variants in a mouse model of hypertension, but with uncertain conclusions." (PMID 36329530, 2022). "Whether CD300LG possibly contributes to the effect of aldosterone on vascular endothelium and lymphocyte migration, and whether this association represents a specific trait of aldosterone-induced hypertension, remains to be established." (PMID 36329530, 2022).
type 2 diabetes (1 paper, 2024). "Serum CD300LG levels were also positively associated with fat mass and fat free mass, and negatively associated with glucometabolic traits, including serum glucose levels, Hb1Ac, and the risk of having type 2 diabetes." (PMID 39190027, 2024). "Moreover, serum CD300LG levels were negatively associated with glucose levels and type 2 diabetes in the UK Biobank, and these associations might be causal based on MR analysis." (PMID 39190027, 2024). "CD300LG may be a promising exercise biomarker and a therapeutic target in type 2 diabetes." (PMID 39190027, 2024).
cancer (7 papers, 2019 to 2025). A tumor composed of atypical neoplastic, often pleomorphic cells that invade other tissues. "Overall, CD300A‐CD300LF were more often upregulated in cancers; whereas downregulation of CD300LG in tumors was more commonly seen." (PMID 35642341, 2023). "It is hypothesized that it may be involved in recruitment of immune cells, and that CD300LG down-regulation results in immune escape of cancer cells." (PMID 31238876, 2019). "However, CD300LG was only prognostically relevant in a few cancers." (PMID 35642341, 2023). "Therefore, we speculated that CD300LG probably affected transendothelial migration of CRC cancer cells by regulating the response of cancer cells to the immune microenvironment, which will be confirmed in our future studies." (PMID 34366718, 2021). "In accordance to our findings, CD300LG was found to be down-regulated in AR+ TNBC tissues when compared with adjacent normal studies, but its role in cancer is still unknown." (PMID 31238876, 2019). "Furthermore, we also determined that higher CD300LG levels, but not PTPRO, IL6ST or CD48, were associated with better overall survival in cancer patients." (PMID 38386350, 2024).
tumor (5 papers, 2013 to 2025). "Thus, it is likely that tumor-associated factors modulate nepmucin/CD300LG expression, although further study is required to identify the factors." (PMID 24376728, 2013). "It was also down-regulated in tumors and tumor-draining lymph nodes, indicating that nepmucin/CD300LG expression is negatively regulated by locally produced signals under these circumstances." (PMID 24376728, 2013). "The nepmucin/CD300LG expression was rapidly down-regulated by inflammatory signals or tumor-derived factors, and it was induced in the chronically inflamed pancreatic islets of NOD mice." (PMID 24376728, 2013). "The down-regulation of nepmucin/CD300LG expression in tumor blood vessels might also play a role in making immune effector cells inaccessible to tumor tissues." (PMID 24376728, 2013). "However, together with the lower expression levels of multiple glycosyl transferases, particularly Chst4, the overall lower level of Podxl, Glycam1, and Cd300lg in PNAd+ TEC may also contribute to the lower level of PNAd expression on the tumor vasculature." (PMID 36189308, 2022). "WT1, COL11A1, FGF5, and IGFL2 were up-regulated in tumor tissues, while GFAP and CD300LG were down-regulated." (PMID 33987034, 2021). "CD300LG and BTNL9, which exhibited more than 32-fold downregulation in all the tumor transcriptomes, showed a very high differential expression patterns." (PMID 31182966, 2019). "The expression level of CD300LG (2343 RPKM) and BTNL9 (7326 RPKM) were very high in normal tissues but very low in the tumor transcriptome (56 RPKM and 283 RPKM, respectively)." (PMID 31182966, 2019). "An interesting question is the biological rationale for the absence of nepmucin/CD300LG expression from immunologically privileged sites such as the brain, testis, and uterus, and also the tumor-related tissues." (PMID 24376728, 2013).
CD300LG also shares sentences with these, for which no sentence is quoted: gastric cancer (1 paper); invasive ductal breast carcinoma (1); lung adenocarcinoma (1); Osteopenia (1).